CEP55 (centrosomal protein 55)
Diseases named in the same sentence as CEP55 in open-access papers (continued):
Sharing a sentence is not in itself a finding about the gene and the disease.
tumor (continued). "Again, the dysregulation of CEP55, CLDN4, CHAF1A, H19 and STEAP4 have been found to significantly correlate with CRC tumor stage, aggressiveness, metastasis and poor prognosis." (PMID 30823889, 2019). "The downregulated MCOLN3 and SLC25A45 with HR < 1 were considered as tumor suppressors, whereas the upregulated COL17A1, CEP55, KLK10, MET, ITGB6, ANKRD22, and ARNTL2 with HR > 1 were regarded as oncogenes." (PMID 31612115, 2019). "Upregulation of CEP55 activates the PI3K/AKT signaling pathway in a concentration-dependent manner and promotes tumor proliferation, invasion, and metastasis." (PMID 31612115, 2019). "The mRNA expression levels of COL17A1, CEP55, KLK10, MET, ITGB6, ANKRD22, and ARNTL2 were significantly increased in PAAD tumor tissue." (PMID 31612115, 2019). "In the clinical specimens, CEP55 mRNA and protein levels were elevated significantly in the nine PANC tissue samples compared with those in three adjacent non-tumour tissues." (PMID 28724890, 2017). "Additionally, these cells exhibit specific upregulation of CEP55, PBK, BIRC5, STMN1, MT2 A, and CKS1B, all of which are related to tumor inflammatory responses." (PMID 40524208, 2025). "By using Sangerbox, we found a significant correlation between CEP55 expression levels and tumor M stage (AJCC TNM stage, M0 = without metastasis, M1 = with metastasis) stage." (PMID 40918457, 2025). "Flow cytometry analysis revealed that CEP55 knockdown in tumor cells decreased the expression of exhaustion markers PD‐1 and TIM‐3 on CD8+ T cells, indicating that reduced CEP55 expression may reverse T cell exhaustion and restore functionality (p < 0.05)." (PMID 40236779, 2025). "IHC analysis also revealed that in patients with low CEP55 expression, the lymphocyte subpopulation infiltration in the tumor microenvironment was predominantly CD8+ cells, whereas in patients with high CEP55 expression, the infiltration was predominantly CD4+ cells." (PMID 40386043, 2025). "This is a critical aspect of this study because it suggests that CEP55 upregulation is not an abrupt change but a gradual process accompanying each phase of tumor growth in CRC." (PMID 38250876, 2024). "Furthermore, the CEP55 knockout increased CD8+ T cell infiltration and granzyme B production, indicating improved anti-tumor immunity." (PMID 38250876, 2024). "Notably, treating the CEP55 KO tumor with anti-PD1 significantly reduced tumor volume compared to the control tumor treated with anti-PD1 and the CEP55 KO tumor treated with IgG2b isotype." (PMID 38250876, 2024). "Starting with MDSCs, around 90% of the analyzed tumors demonstrated a positive correlation between MDSC and CEP55, with only one tumor, THCA, that showed a negative correlation between the same factors." (PMID 37175004, 2023). "The current study reported that KIRC, LGG, LIHC, UCEC, HNSC, OV, and PAAD showed a positive correlation between CEP55 expression and tumor grade, while ACC, KIRC, KIRP, LIHC, LUAD, UCEC, and LUSC showed the same correlation between CEP55 expression and tumor stage." (PMID 37175004, 2023). "CEACAM1, CEP55 and MELK were involved in tumor, inflammation, necrosis, and proliferation." (PMID 37589542, 2023). "Centrosomal protein (CEP55) was found on tumor-derived exosomes in HNCC, but not in primary human oral keratinocytes." (PMID 37304135, 2023). "Consistent with previous findings, CEP55 was documented to be more abundant in tumor tissues than in non-tumor tissues in both the ICGC and GSE14520 datasets." (PMID 37484531, 2023). "In addition, the potential of tumor-expressing CEP55 as a TAA for modulating immune activity should be explored, possibly through the identification and clonal tracing of CEP55 antigen-specific T cells in the context of human tumors." (PMID 37484531, 2023). "No expression of CEP55 was observed in normal lung tissues, while medium expression of CEP55 was observed in tumor tissues." (PMID 35178291, 2022).
tumor (continued). "Indeed, the present study showed that CCNA2, CEP55, KIF11, KIF4A, and ZWINT were the top five genes that were significantly and positively correlated with CDK1 in all tumor types from the TCGA database." (PMID 35681641, 2022). "By randomly assessing the potential target genes in the tumor samples, we have found that up-regulated SOX9, RASA1, CEP55 and MAP4K4, the target genes of miR-582, might play important roles in LUAD tumorigenesis." (PMID 33510968, 2021). "In RCC cells, M2-EV-derived miR-342-3p could specifically bind to NEDD4L and consequently elevate CEP55 protein expression via suppressing NEDD4L, thereby exerting tumor-promoting effects." (PMID 37305161, 2021). "The acidosis-related signature is composed of seven key genes (ARNTL2, DKK1, CEP55, CTSV, MYEOV, DSG2, and GBP2), all of which have elevated expression levels in PC tumor tissues compared with normal tissues and are all related to adverse clinical outcomes in patients with PC." (PMID 34993253, 2021). "However, the staining intensity or the range of positive areas of CEP55, KIF23, MYBL2, and RACGAP1 was higher in tumor samples (medium or high levels) than in non-tumor tissue." (PMID 34093635, 2021). "We will further verify the expression of CEP55 in Fn-infected CRC cell lines, animal models and patients and elucidate the molecular mechanism of CEP55 in the proliferation, invasion and metastasis of tumor cells induced by Fn infection." (PMID 34650590, 2021). "Interestingly, many of these genes are known to be involved in cell-cycle function (CDK2, CDK6, CCNB1, CEP55, CENPF), transcriptional regulation/tumor suppression (FOXO3, TOP2A), DNA-damage response (ASPM, XRCC4), and tumor progression (CYR61, MACC1, CXCR4)." (PMID 28482906, 2017). "Furthermore, SW480-derived microvesicles are enriched with CENPE, KIF15, CEP55, CCNA2, NEK2, PBK, and CDK8 that are M-phase-related transcripts involved in tumorigenesis and tumor progression." (PMID 19930720, 2009). "Therefore, we examined the phosphorylation sites of CEP55 and the changes in CEP55 phosphorylation levels between primary tumor tissues and normal tissues." (PMID 37887301, 2023). "However, a comprehensive picture of CEP55 in the tumor immune microenvironment has not yet been reported, and small therapeutic compounds targeting CEP55 remain elusive." (PMID 37484531, 2023). "Following that, the top 100 correlated proteins with CEP55 were collected from the GEPIA2 database, where the proteins KIF11, MK167, CDK1, PLK1, and CCNA2 represented the top 5 proteins correlated with CEP55 in the tumor microenvironment that influence immune cells in TME." (PMID 37175004, 2023). "In addition, we revealed that high levels of CEP55 significantly affected the pathological staging of tumors in BRCA, HNSC, and LUAD, suggesting that CEP55 overexpression may be involved in tumor progression and invasion." (PMID 37887301, 2023). "Although we did not observe a significant change in the tumor infiltration of CD4+ T cells, it is worth noting that CEP55 KO-derived tumors showed a significantly elevated CD8+ T cell infiltration." (PMID 38250876, 2024). "The relative expression levels of CDKN3, MKI67, CEP55, SPAG5, AURKA, TOP2A were consistent with the results of bioinformatics analysis (P < 0.05), while the expression levels of UBE2C, CHEK1 and BIRC5 in tumor samples were not significantly different from adjacent normal samples." (PMID 35178291, 2022).
infection (6 papers, 2021 to 2025). The state of being infected such as from the introduction of a foreign agent such as serum, vaccine, antigenic substance or organism. "Given the extent of apoptosis observed in our mouse model, we characterized the effect of CEP55 knock-down in the cerebral organoids at 24 hours post-infection." (PMID 34710087, 2021).
neurological disorders (1 paper, 2025). "Recent findings indicate that CEP55, via interacting with polyubiquitin, plays an important role in cell division, and defects in CEP55′s ubiquitin-binding activity may be an underlying mechanism for CEP55 mutation-caused neurological disorders." (PMID 39996775, 2025).
CEP55 also shares sentences with these, for which no sentence is quoted: HIV-1 infection (3 papers); hydranencephaly (3); bladder transitional cell carcinoma (2); COVID-19 (2); prostate adenocarcinoma (2); acute myeloid leukemia (1); adult benign familial myoclonic epilepsy (1); anaplastic thyroid cancer (1); Anhydramnios (1); bacterial infection (1); bone cancer (1); cardiomyopathies (1); clear renal cell carcinoma (1); esophagus adenocarcinoma (1); genetic disorder (1); holoprosencephaly (1); Insulin resistance (1); invasive ductal carcinoma (1); kidney cancer (1); liver disease (1); Meckel-Gruber syndrome (1); metastasis (1); ovarian serous cystadenocarcinoma (1); Pan (1); Pancreas (1); pancreatic ductal adenocarcinoma (1); papillary renal cell carcinoma (1); paraganglioma (1); pheochromocytoma (1); porencephaly (1).
A further 10 diseases each share a sentence with CEP55 in 1 paper.